KRT18 (keratin 18)
Diseases named in the same sentence as KRT18 in open-access papers (continued):
Sharing a sentence is not in itself a finding about the gene and the disease.
COVID-19 (110 papers, 2020 to 2026). A disease caused by infection with severe acute respiratory syndrome coronavirus 2. "This study aimed to examine the influence of severe acute respiratory syndrome coronavirus 2 (SARS-CoV-2) infection on pregnancy in cytokeratin-18 (K18)-hACE2 transgenic mice." (PMID 36108690, 2023). "The K18-hACE2 mouse model (transgenic expression of human ACE2 (hACE2) under a cytokeratin 18 promoter) offers a stringent system for testing the efficacy of DAAs and HDAs against severe disease and mortality after SARS-CoV-2 infection." (PMID 35344983, 2022). "Transgenic mice carrying the human ACE2 receptor under the control of the keratin 18 promoter (K18-hACE2), a widely used COVID-19 model, also served in the current co-infection study." (PMID 38932155, 2024). "The most commonly used K18-hACE2 model, where hACE2 is expressed under control of the human keratin 18 promotor, in addition to the murine ACE2, appears to be the most susceptible COVID-19 model reported to date using human SARS-CoV-2 isolates." (PMID 37638020, 2023). "The human keratin 18 promoter directs human ACE2 expression to epithelia, specifically the airway epithelia, where the viral infection typically begins, making K18-hACE2 susceptible to SARS-CoV-2, therefore useful for studying antiviral therapies against COVID-19." (PMID 36423193, 2022). "Nevertheless, in a mouse model of COVID-19, genetically modified mice expressing human ACE2 under the cytokeratin 18 (K18) promoter have been used." (PMID 35062298, 2022). "To compare our data with a widely used mouse model of COVID-19, we infected KRT18-hACE2 transgenic mice that express human ACE2 under control of the human keratin 18 promoter with either 1 × 103 or 1 × 104 TCID50 of BavPat1 and monitored the disease course over 7 days." (PMID 35023830, 2022). "The widely used K18-hACE2 transgenic mouse model expresses the SARS-CoV-2 receptor, human angiotensin-converting enzyme 2 (hACE2) from the keratin 18 promoter, and provides a severe model of COVID-19." (PMID 36680179, 2022). "We then tested the effects of IKE and NAC in vivo using keratin 18 (K18)-hACE2 mice, which express human ACE2 receptor under the K18 promoter in the epithelia, including airway epithelial cells, and recapitulate several aspects of severe and non-severe COVID-19 in humans." (PMID 38305139, 2024).
liver fibrosis (54 papers, 2012 to 2026). "Fibrosis-4 (FIB-4) and aspartate aminotransferase (AST)-to-Platelet Ratio Index (APRI) scores were recorded, and blood cytokeratin-18 (CK-18) levels were measured to assess hepatic fibrosis." (PMID 41085150, 2025). "The triglyceride-glucose (TyG) index was commonly associated with early-stage NAFLD screening; cytokeratin-18 (CK18) was linked to NASH detection, while adiponectin and osteopontin (OPN) were related to liver fibrosis." (PMID 40951433, 2025). "If the patients were stratified according to the cytokeratin 18 fragment (CK-18) level, an established marker for liver fibrosis and increased inflammatory activity, only Th17/rTreg ratio differentiated between early and advanced stages of MASLD." (PMID 40918132, 2025). "Immunohistochemical (IHC) analysis of tissue sections showed decreased expression of ALB, AAT, and KRT18 within the liver fibrosis region of CCL4‐induced mice." (PMID 40619613, 2025). "Plasma cytokeratin 18 (CK18), a by-product of hepatocyte-caspase activity, has been identified as a novel biomarker for liver fibrosis in both adult and pediatric NAFLD cases." (PMID 29874807, 2018). "Therefore, we aimed to evaluate rs738409 patanin-like phospholipase domain-containing protein (PNPLA3) and rs499765 FGF21 polymorphisms in T2D, and their association with NAFLD, liver fibrosis, and serum biomarkers (FGF21 and cytokeratin 18 levels)." (PMID 35630668, 2022). "At baseline, mean alanine aminotransferase (ALT), aspartate aminotransferase (AST), fibrosis-4 (FIB-4) index, Enhanced Liver Fibrosis (ELF) score, cytokeratin-18 (K-18) and serum pro-peptide collagen III (pro-C3) were normal or modestly elevated." (PMID 38858523, 2024). "Congruently, the stage of liver fibrosis did not correlate with the parameters of hepatocyte apoptosis or necrosis (fragments M30 and M65 of cytokeratin-18)." (PMID 25350286, 2014). "One approach utilizes the testing of biochemical markers of liver fibrosis: hyaluronic acid, adiponectin, high-sensitivity CRP, type IV collagen, serum IL-6, leptin, laminin, c-peptide, and cytokeratin-18." (PMID 23555578, 2013). "In addition to clinical scoring systems, circulating biomarkers, including cytokeratin-18 (CK-18) fragments, procollagen III N-terminal peptide (PIIINP), hyaluronic acid, and TIMP-1, have been investigated for their utility in detecting steatohepatitis and liver fibrosis." (PMID 40869400, 2025). "Therefore, the detection of activated caspase or the cytokeratin-18 (CK-18) fragment cleaved by caspase 3 are potentially noninvasive ways to detect human MAFLD and liver fibrosis." (PMID 33962586, 2021).
steatosis (49 papers, 2011 to 2026). Increased lipid within the cytoplasm of cells. "Keratin 18 deficiency in mice (Krt18−/− mice) results in mild to moderate degree of steatosis after 17–20 months from birth, with lobular inflammation and mononuclear cell infiltration, an image that closely resembles NASH in humans." (PMID 36555433, 2022). "However, the number of animals with fatty liver as well as the steatosis grades increased with age and keratin deficiency status: in 17-20-months-old mice only mild steatosis was found in about one third of wt mice whereas it was mild to moderate in almost all Krt18+/− and Krt18−/− mice." (PMID 27689336, 2016). "In aged male and female Krt18+/− mice the degree of steatosis essentially equaled that of Krt18−/− livers in most animals." (PMID 27689336, 2016). "We show that aged (17-20-months-old) Krt18−/− mice spontaneously develop morphologic features of SH as well as liver tumors preceded in younger animals by steatosis as possible “first hit”." (PMID 27689336, 2016). "From the large spectrum of biomarkers tested, cytokeratin-18 fragments have shown the most consistent results for differentiating NASH from steatosis." (PMID 25350286, 2014). "Of note, IGSF9, ADAMTSL2, KRT18, and RIDA were associated with both steatosis and fibrosis." (PMID 39426127, 2024). "In Krt18+/− animals (particularly in males) hepatocytes, predominantly located in zone 3, showed clear cytoplasm with more intense staining of the cell periphery and mild macrovesicular steatosis." (PMID 27689336, 2016). "Also, the sensitivity and specificity of cytokeratin-18 fragments in the discrimination between simple steatosis and NASH was higher (75% sensitivity and 81% specificity for M30; 80% sensitivity and 82% sensitivity for M65)." (PMID 25350286, 2014). "Promising biomarkers, which are related to NASH and may help differentiate steatosis from steatohepatitis, are cytokeratin-18 (CK-18), the terminal peptide of procollagen III (PIIINP), IL-6, TNF-α, the chemokines MCP-1 and RANTES, and fibroblast growth factor 21 (FGF21)." (PMID 35877216, 2022). "Among these, cytokeratin-18 (CK-18), a fragment released during hepatocyte apoptosis, is the most extensively studied serum biomarker for distinguishing NASH from simple steatosis." (PMID 40734888, 2025). "Biomarkers of apoptosis like Cytokeratin-18 are strongly increased in NASH patients and distinguish between simple steatosis and NASH." (PMID 24963148, 2014). "Serum concentrations of cytokeratin-18 fragments M30 and M65 were significantly higher in patients with NASH, compared to patients with simple steatosis." (PMID 25350286, 2014). "Another limitation was the absence of direct comparisons with other biomarkers such as ELF, Fibrospect, Fibrometer and Fibroscan for fibrosis, cytokeratin 18 for NASH, and magnetic resonance imaging and spectroscopy for steatosis." (PMID 22431959, 2012). "After stratification by cytokeratin-18 tertiles, a significant progression of body mass index, HOMA-IR, triglycerides, urinary 8-iso-PGF2α, soluble NOX2-derived peptide, and of the prevalence of diabetes and severe steatosis was found, while HDL-cholesterol and adiponectin progressively decreased." (PMID 24678423, 2014). "Moreover, the levels of the 12 serum-based markers were examined in relation to the CAP values; while MMP-9 levels were significantly lower, keratin-18 and ghrelin levels were significantly higher in patients with steatosis >S1 (CAP ≥302dB/m) than those without." (PMID 34813621, 2021).
liver disease (48 papers, 2010 to 2026). "Keratin 8 (K8) and keratin 18 (K18) are expressed mainly in adult hepatocytes, and mutations of this K8/K18 pair can lead to various liver diseases." (PMID 33324348, 2020). "Genetic mouse models highlighted the function of KRTs in protecting hepatocytes from apoptosis and necrosis, and mutations within the KRT8 and KRT18 genes are linked to the progression of liver disease of multiple etiologies." (PMID 31216713, 2019). "Cytokeratin-18 (CK-18), an intermediate filament protein found mainly in epithelial cells, has become a possible indicator for predicting outcomes in liver diseases." (PMID 39023658, 2024). "Circulating cytokeratin-18 and its fragments are a widely endorsed marker of necrosis and apoptosis in liver diseases that is also used in the follow-up of some epithelial oncological processes." (PMID 36836178, 2023). "In particular, KRT18 release into the extracellular space is mediated by hepatocellular damage and is therefore a commonly-used, non-invasive marker of liver diseases." (PMID 31216713, 2019). "The observation that KRT8 and KRT18 variants associate with progression of fibrosis during CHC encouraged us to use hepatitis C virus, a major cause of severe liver diseases, as a pathogenic model." (PMID 31216713, 2019). "Serum level of ALT is commonly used as a surrogate indicator for evaluating liver histology in various liver diseases, and ALT seems to be more closely associated with steatohepatitis than other biomarkers, e.g. cytokeratin-18." (PMID 28103934, 2017). "Cytokeratin-18 fragments in peripheral blood are generated by apoptosis and full-length cytokeratin-18 generated by necrosis, and are elevated in a variety of liver diseases including NASH and viral hepatitis." (PMID 26795831, 2016). "In our study, cytokeratin-18, a marker of liver disease severity, was an independent predictor of urinary 8-iso PGF2α, thus suggesting also a possible effect of fatty liver on systemic oxidative stress." (PMID 24758604, 2014). "Moreover 8-iso-PGF2α was an independent predictor of cytokeratin-18 (CK-18), a marker of apoptosis reflecting liver disease severity." (PMID 35740032, 2022). "For example, the phenotypic characterisation of various K8 and K18 knockout and transgenic mouse lines has been important in helping to demonstrate an association between predisposing KRT8 and KRT18 gene mutations in humans with various types of liver disease." (PMID 23741325, 2013). "Serum keratin-18 (CK18) levels are increased in liver diseases and may be biomarkers of outcome." (PMID 34207346, 2021).
Hepatic steatosis (43 papers, 2011 to 2026). Steatosis is a term used to denote lipid accumulation within hepatocytes. "Acromegaly has also been linked to lower hepatic steatosis, higher liver stiffness, and elevated IGF binding protein 7 and cytokeratin 18 levels, with fibrosis being more common and hepatic steatosis inversely related to GH levels." (PMID 40725515, 2025). "Metabolic dysfunction-associated fatty liver disease (MASLD) is a common liver and health issue associated with heightened cardiovascular disease (CVD) risk, with Cytokeratin 18 (CK-18) as a marker of liver injury across the MASLD to cirrhosis spectrum." (PMID 39595946, 2024). "Regarding liver status, cytokeratin-18 fragments and several non-invasive scores of fatty liver were also assessed." (PMID 28657604, 2017). "In this study, Resveratrol supplementation was associated with a significant reduction in liver enzyme alanine aminotransferase, inflammatory cytokines, nuclear factor κB activity, serum cytokeratin-18, and hepatic steatosis grade, as compared with placebo supplementation (P < .05)." (PMID 27367854, 2016). "Cytokeratin 18 (CK18) and insulin-like growth factor binding protein 7 (IGFBP7) increase in liver steatosis and fibrosis." (PMID 38709454, 2024). "The most important are: Fatty liver index (FLI), Hepatic steatosis index (HSI), SteatoTest, NAFL screening score, Cytokeratin-18 (CK18), and Fibroblast growth factor 21 (FGF21)." (PMID 32349225, 2020). "When combined as a biomarker panel in an algorithm; IL-6, adiponectin and cytokeratin 18 (CK18) displayed an AUROC of 0.90 with sensitivity and specificity of 85% and 86% respectively for discriminating fatty liver alone from NASH." (PMID 31291245, 2019). "The aim of this study was to appraise the relationship between serum fragmented cytokeratin-18(CK-18), controlled attenuation parameter (CAP), and liver steatosis assessed by ultrasound (US) in nonalcoholic fatty liver disease (NAFLD) patients." (PMID 30363686, 2018). "The study, which involved an approximate intake of 50 g per day, found an increase in hepatic steatosis and no significant changes in inflammation markers such as IL-6, IL-8 and Cytokeratin-18 (CK-18)." (PMID 41010458, 2025). "Cytokeratin (CK-18), or KRT18, is a marker of apoptosis and probably the most widely studied biomarker for predicting the presence of non-alcoholic steatohepatitis (NASH) in patients with hepatic steatosis." (PMID 35204498, 2022). "Patients with non-alcoholic fatty liver had higher (p < 0.001) mean values of urinary 8-iso-PGF2α and of serum soluble NOX2-derived peptide, alanine aminotransferase, Cytokeratin-18 and homeostasis model of insulin resistance and lower values of serum adiponectin as compared to those without." (PMID 24758604, 2014). "Recently, a specific byproduct of apoptosis in hepatocytes, caspase-generated cytokeratin-18 (CK-18) fragments, has been shown to be significantly elevated in patients with NASH compared with subjects with fatty liver or healthy controls, with an AUC of 0.93 for predicting NASH." (PMID 22110476, 2012). "Other novel non-invasive detection methods such as instantaneous elastography, magnetic resonance spectroscopy and cytokeratin 18 (CK-18) have not been promoted in clinical detection.Therefore, this study relied primarily on ultrasound results for the diagnosis of hepatic steatosis." (PMID 39980852, 2025).
prostate carcinoma (31 papers, 2006 to 2026). A carcinoma that arises from epithelial cells of the prostate gland. "In breast and prostate cancer, downregulation of KRT18 was associated with increased aggressiveness." (PMID 41209344, 2025). "KRT18 is a well-known epithelial marker in diagnostic histopathology and its downregulation is associated with prostate cancer aggressiveness." (PMID 35870994, 2022). "The same study used western blotting to demonstrate a higher amount of keratin 18 in EVs derived from the plasma of patients with prostate cancer, compared to healthy patients." (PMID 39057100, 2024). "In PCa, expression of KRT8, KRT18, and KRT19 by tumor cells disseminated to the bone, is associated with a worse prognosis; KRT18 and KRT5 expression correlates with metastases and hormone-escaped prostate carcinomas, respectively." (PMID 36033462, 2022). "The release of caspase-cleaved and total keratin 18 (ccK18 and K18, respectively) to serum has been well documented in clinical studies after treatment of breast and prostate cancer patients with cytotoxic drugs." (PMID 22870292, 2012). "Among the proteins enriched in LO, cytokeratin 18 (CK18) was one of the most abundant (within the top 5th percentile) and was used to develop an assay to detect LO in the circulation and tissues of mice and patients with prostate cancer." (PMID 25857301, 2015). "The same upregulation of cytokeratin 18 and E-cadherin expression was obtained when CDK11p58 expression was knocked down, further supporting our conclusions that CDK11p58 impacts prostate cancer cell migration and invasion through regulation of SPDEF protein stability." (PMID 26885618, 2016). "To identify metastasis-specific alterations in the composition and gene expression of KP_Pos (KRT18+PTPRC+) cells, we conducted an integrated single-cell transcriptomic analysis of benign, primary, and metastatic prostate cancer tissues." (PMID 41355965, 2026). "We found that depending on age of prostate cancer patients and Gleason score EMT genes with distinctly altered expression are: KRT18, KRT19, MUC1 and COL4A1, CTNNB1, SNAI2, ZEB1 and MMP3." (PMID 29206234, 2017). "The differences between oncosomes and LOs at the cargo level are not clarified yet, but for prostate cancer, it was shown that cytokeratin 18 (CK18) was one of the most abundant proteins in LOs." (PMID 40926108, 2025). "One of the proteins localized in oncosomes, cytokeratin 18 (CK18), has been found to be highly prevalent (within the top fifth percentile) and was used in the creation of a test to detect oncosomes in tissues and circulatory of both human and mouse prostate cancer patients." (PMID 39132504, 2024).
viral infection (29 papers, 2010 to 2025). "The experimental model used in our study, transgenic mice expressing the human ACE2 receptor under control of cytokeratin-18 promoter (K18-hACE2), develops a severe viral disease after SARS-CoV-2 inoculation." (PMID 36010648, 2022).
fibrosis (27 papers, 2013 to 2025). the formation of excess fibrous connective tissue in an organ or tissue in a reparative or reactive process. "Another notable marker is cytokeratin-18 (CK-18), which reflects hepatocyte apoptosis and is particularly elevated in metabolic dysfunction-associated steatohepatitis (MASH)-related fibrosis." (PMID 40643544, 2025).
non-alcoholic steatohepatitis (26 papers, 2010 to 2025). "Cytokeratin 18 is a marker of apoptosis in liver injury, and plasma homocysteine levels can distinguish metabolic dysfunction-associated steatohepatitis (MASH) from simple steatosis." (PMID 41406476, 2025). "Association between elevated cytokeratin 18 (CK-18) levels and hepatocyte death has made circulating CK-18 a candidate biomarker to differentiate non-alcoholic fatty liver from non-alcoholic steatohepatitis (NASH)." (PMID 32915852, 2020). "Plasma cytokeratin-18 (CK-18) fragment levels correlate with the magnitude of hepatocyte apoptosis and have recently been proposed to independently predict the presence of non-alcoholic steatohepatitis (NASH)." (PMID 37189422, 2023). "KRT8/KRT18 variations listed in the ClinVar database may be involved in nonalcoholic steatohepatitis (NASH), in oxidative stress to the liver, indirectly leading to cirrhosis, and in increased formation of fibrosis during chronic hepatitis C infection." (PMID 34991727, 2022). "On the other hand, cytokeratin 18 (CK-18) antibodies M65 and M30 may be better biomarkers of nonalcoholic steatohepatitis (NASH) than of advanced fibrosis." (PMID 34971370, 2022). "Alterations in apoptosis, as reflected by circulating Cytokeratin 18 (CK18), are involved in the progression of non-alcoholic fatty liver disease (NAFLD) to non-alcoholic steatohepatitis and atherogenesis." (PMID 37509164, 2023). "Because non-alcoholic steatohepatitis (NASH), the progressive form of NAFLD is characterized by inflammation and cellular injury, we evaluated the impact of AAA-1 on the expression of the hepatocellular injury marker Cytokeratin-18 (CK-18)." (PMID 37798764, 2023).